NAA20 (N-alpha-acetyltransferase 20, NatB catalytic subunit)
Description:
Catalytic subunit of the NatB complex which catalyzes acetylation of the N-terminal methionine residues of peptides beginning with Met-Asp, Met-Glu, Met-Asn and Met-Gln. Proteins with cell cycle functions are overrepresented in the pool of NatB substrates. Required for maintaining the structure and function of actomyosin fibers and for proper cellular migration.
Synonyms: NAT5; dJ1002M8.1; NAT3; MRT73; NAT3P; NAT5P
Tractability: Small molecule: a structure with a bound ligand is known. PROTAC: ubiquitination databases record sites on it; its protein half-life has been measured.
Gene: Protein-coding gene on chromosome 20 (20,017,310 to 20,033,655, forward strand). Ensembl gene ENSG00000173418.
Subcellular location: Cytoplasm; Nucleus
Subcellular location (Human Protein Atlas): Cytosol
Gene Ontology:
Molecular function: protein binding; protein-N-terminal amino-acid acetyltransferase activity; acyltransferase activity, transferring groups other than amino-acyl groups; protein N-terminal-methionine acetyltransferase activity
Biological process: N-terminal peptidyl-aspartic acid acetylation; N-terminal peptidyl-glutamic acid acetylation; N-terminal peptidyl-glutamine acetylation; N-terminal protein amino acid acetylation; regulation of actin cytoskeleton organization
Cellular component: cytoplasm; cytosol; NatB complex; nucleus
Genetic constraint (gnomAD): Loss-of-function variants: 15 observed, 16.57 expected, observed/expected ratio (o/e) 0.91, 90% interval 0.61 to 1.39. The upper end of that interval is the gene's LOEUF score, 1.39, which puts it in group 5 of 6, group 1 being the genes least tolerant of losing a copy. Missense variants: 134 observed, 192.27 expected, observed/expected ratio (o/e) 0.7, 90% interval 0.61 to 0.8. Synonymous variants: 72 observed, 68.69 expected, observed/expected ratio (o/e) 1.05, 90% interval 0.87 to 1.27.
Homologues: Orthologues: chimpanzee NAA20 (100% identical), guinea pig NAA20 (100% identical), macaque NAA20 (100% identical), mouse Naa20 (100% identical), rabbit NAA20 (100% identical), rat Naa20 (100% identical), zebrafish naa20 (99% identical), tropical clawed frog naa20 (97% identical), pig NAA20 (91% identical), Drosophila melanogaster Naa20A (67% identical), Caenorhabditis elegans natb-1 (60% identical). Paralogues in human: NAA10 (31% identical), NAA11 (30% identical), NAA30 (24% identical), NAA50 (18% identical).
Diseases named in the same sentence as NAA20 in open-access papers:
NAA20 is named in the same sentence as 11 diseases in open-access papers, as found by Europe PMC text mining. Sharing a sentence is not in itself a finding about the gene and the disease. The quoted sentences say what the papers report.
esophageal carcinoma (1 paper, 2020). A primary or metastatic malignant neoplasm involving the esophagus. "The cg10759293 probe located within the first intron of NAA20 displayed both the most prominent decreases in its methylation and strongest anti-correlation with gene expression in two tumour types, lung squamous carcinoma (LUSC, r = −0.61) and esophageal carcinoma (ESCA, r = −0.56)." (PMID 32942614, 2020).
hepatocellular carcinoma (1 paper, 2020). A malignant tumor that arises from hepatocytes. "N-α-acetyltransferase 20 (Naa20), which is a catalytic subunit of the N-terminal acetyltransferase B (NatB) complex, has recently been reported to be implicated in hepatocellular carcinoma (HCC) progression and autophagy, but the underlying mechanism remains unclear." (PMID 33219302, 2020).
male infertility (1 paper, 2023). The inability of the male to effect fertilization of an ovum after a specified period of unprotected intercourse. "However, pleiotropic developmental defects could preclude the detection of male infertility, and tissue-specific analyses in rodents would be required to directly test the role of the mammalian NAA20 in sperm differentiation." (PMID 37872135, 2023).
microcephaly (1 paper, 2021). A congenital or acquired developmental disorder in which the circumference of the head is smaller than normal for the person's age and sex. "In conclusion, we present here pathogenic NAA20 variants that disrupt NAA20 function and support an essentialrole for NatB-mediated N-terminal acetylation in human development and physiology.All affected individuals display DD, ID, and microcephaly." (PMID 34230638, 2021).
tumour (5 papers, 2017 to 2025). "This analysis further indicates that Naa20 may be implicated in promoting HCC tumor progression." (PMID 33219302, 2020). "Our group has previously shown that in HCC, the expression of the NatB catalytic subunit NAA20 correlates with tumor progression." (PMID 28498797, 2017). "However, we showed here that LKB1 may function as a tumor suppressor in tumorigenesis in a manner related to Naa20 in HCC cells." (PMID 33219302, 2020). "Importantly, Naa20 negatively regulated the LKB1–AMPK axis to promote the mTOR signaling pathway through Nt-acetylation of LKB1, which contributes to tumor progression and autophagy in HCC." (PMID 33219302, 2020). "To better define the role of hNatB in human HCC development we have now analyzed both NAA20 and NAA25 protein expression in paired tumor and non-tumor samples from 27 HCC patients (74% stage BCLC A and 26% stage B) treated with liver resection or transplantation." (PMID 28498797, 2017). "Interestingly, both subunits were up- or downregulated in 74% of analyzed tumor samples, indicating the expression of both subunits is co-regulated probably as a consequence of NAA20 degradation when it is not interacting with the accessory subunit NAA25." (PMID 28498797, 2017). "Indeed, we observed that in GBM, tumours with gain in the copy numbers of NAA25, the protein levels of NAA20, but not its transcript levels, were significantly increased." (PMID 38864963, 2025).
NAA20 also shares sentences with these, for which no sentence is quoted: breast carcinoma (1 paper); cancer (1); Intellectual disability (1); liver cancer (1); myelogenous leukaemia (1); neuroblastoma (1).